AR (androgen receptor)
Diseases named in the same sentence as AR in open-access papers (continued):
Sharing a sentence is not in itself a finding about the gene and the disease.
breast carcinoma (continued). "However, the role of AR in breast cancers is still not fully elucidated and the biology of AR in breast cancer remains incompletely understood." (PMID 28957377, 2017). "Moreover, the expression of AR is correlated with RB1 in patients with TNBC and breast cancer." (PMID 29261702, 2017). "Although these in vivo studies suggested that AR has a role in breast cancer metastasis, most of the current in vivo breast cancer model systems are not clinically relevant and have many limitations which hinder our understanding of the role of AR in breast cancer metastasis." (PMID 29254284, 2017). "Hence it is not surprising that the clinical prognostic role of AR in primary breast cancer varies in different subtypes of breast cancers." (PMID 28474005, 2017). "Further, 60-80% express the androgen receptor, which has been shown to have tissue protective effects in estrogen receptor positive breast cancer, and a more ambiguous response in estrogen receptor negative breast cancers." (PMID 28430630, 2017). "However, despite these emerging data, the role of AR in breast cancers is still not fully elucidated and the biology of AR in breast cancer remains incompletely understood." (PMID 28957377, 2017). "The prognostic role of AR in ERα-negative breast cancer is debatable." (PMID 28474005, 2017). "The roles of changes in the AR or FOXA1 genes have not been much studied in female breast cancers." (PMID 29137314, 2017). "Since different molecular mechanisms between AR and FOXA1 signaling pathways have been suggested in ER-negative breast cancers, the clinical implications of AR and FOXA1 status on patient prognosis should be further investigated to improve the survival of patients with heterogeneous breast cancers." (PMID 29137314, 2017). "The expression of AR was found in 50% to 60% of ERα-negative/HER2-positive breast cancer." (PMID 28474005, 2017). "AR antagonists are not currently used as therapy in breast cancer." (PMID 28474005, 2017). "As was observed with enzalutamide, abiraterone also increased the sensitivity of both AR+ ZR75-1 and AR- MDA MB 231 breast cancer cells to CTL-mediated lysis, confirming the ability of ADT to increase the sensitivity of breast cancer cells to immune-mediated killing regardless of AR status." (PMID 27015557, 2016). "Tumor growth regression with androgens was also observed after the removal of the pituitary, establishing that the effect of androgens is mediated directly through the AR expressed in the breast cancer tissue rather than through an effect on the hypothalamus pituitary hypogonadal axis." (PMID 27918430, 2016). "While AR expression was required for the growth inhibitory effects of enzalutamide on breast cancer cells, both enzalutamide and abiraterone improved the sensitivity of breast cancer cells to immune-mediated lysis independent of detectable AR expression." (PMID 27015557, 2016). "Our studies were able to show, for the first time, that ADT was capable of inducing immunogenic modulation in breast carcinoma cells and that, unlike what was previously seen with prostate carcinoma cells, this immunogenic modulation was not dependent on detectable AR expression." (PMID 27015557, 2016). "However, similar studies concerning the impact of Lin28A on expression of the AR in human breast cancer have not been reported previously." (PMID 27494865, 2016). "This is in agreement with previous findings reported in breast cancer cells, suggesting that the pathway by which p23 acts upon gene expression is conserved across different tissues and cell types, and is not dependent upon AR." (PMID 25241147, 2015).
breast carcinoma (continued). "Early studies showed that DHEAS caused proliferation in T47D breast cancer cells, known to have STS activity, even when cotreated with tamoxifen, implying that androgens influence breast cancer proliferation through AR activation and not just through estrogenic metabolites." (PMID 26213785, 2015). "In certain ERα-negative breast cancer cell lines, AR can stimulate growth and survival." (PMID 26554309, 2015). "Sensitivity to bicalutamide, an oral AR inhibitor, was better in LAR cell lines than in other subtypes and a recent phase II study confirmed the interest of such drug showing a 19% of clinical benefit rate at 24 weeks for ER/PR-negative AR-positive breast cancer patients." (PMID 25973541, 2015). "To this end we decided to explore whether or not PSAP can also activate AR in AI-resistant breast cancer cells in the presence of unconverted endogenous androgens." (PMID 26341737, 2015). "In addition the androgen receptor (AR) is expressed in breast cancer in 60%–70% of tumors regardless of the ER status and has been linked with a good outcome in ER positive tumors." (PMID 24779793, 2014). "Our analysis of 192 women with ER + breast cancers treated with tamoxifen revealed that rather than the level of AR expression, the AR:ER ratio may play a role in disease progression and response to treatment." (PMID 24451109, 2014). "However, the expression of the AR has been described in a number of non-CaP cancers, especially breast cancer." (PMID 25409505, 2014). "Advances in genomic driven classification of breast cancer continue to evolve the subtypes, particularly in TNBC, which can be further divided into: basal-like 1, basal-like 2, immunomodulatory, mesenchymal-like, mesenchymal stem-like, and luminal androgen receptor." (PMID 25566499, 2014). "Nonsteroidal, tissue selective androgen receptor modulators (SARMs) may provide a novel targeted approach to exploit the therapeutic benefits of androgen therapy in breast cancer." (PMID 25072326, 2014). "In the context of a postmenopausal woman on AI therapy (in the absence of estrogen), it is possible that activated AR could mediate protumorigenic pathways in breast cancers." (PMID 24451109, 2014). "Expression of both miR-191 and miR-425 was higher in the ERα positive cell lines, with the exception of MDA-MB-453 (a non-aggressive ERα negative/androgen receptor positive breast cancer cell line but with a gene expression profile that overlaps with ERα positive breast cancer cells)." (PMID 23505378, 2013). "Indeed, a small subset of breast tumours, termed the ‘molecular apocrine’ subtype, which are ERα-negative but express AR, typically express genes normally expressed in ERα-positive breast cancer." (PMID 24049078, 2013). "The role of AR on survival in breast cancer patients is not very clearly known until now." (PMID 24324816, 2013). "Breast cancer is a heterogeneous disease comprised of distinct molecular subtypes that can be generally characterized by the expression status of receptors for estrogen (ER), progesterone (PR), human epidermal growth factor receptor 2 (HER2) and more recently, androgen (AR)." (PMID 24155918, 2013). "Of the 109 patients with breast cancer, 52 (47.7%) were AR-positive and 57(52.3%) were AR-negative." (PMID 24324816, 2013). "However, the relationship between the role of the AR and the menopausal status or age in breast cancer patients has not been reported." (PMID 24403250, 2013). "AR overexpression may provide a new therapeutic target for breast cancer, especially in patients with ER(-) tumors that do not benefit from endocrine or HER2 targeted therapies." (PMID 23663520, 2013). "While proliferation of MCF-7 breast cancer cells has been shown to occur even in the absence of estrogens, the proliferative effect may not be mediated through the androgen receptor pathway." (PMID 24324894, 2013). "Roles of AR in breast cancer development and progression have not been very clearly understood." (PMID 24324816, 2013).
breast carcinoma (continued). "An immunohistochemical analysis indicates that AR and GCDFP-15 are highly and specifically expressed in more than 80% and 90% of patients with SDC, respectively, whereas ER and PgR, well known as common breast carcinoma markers, are very weakly or negatively stained." (PMID 22647549, 2012). "Additionally, approximately 20% of HER2-positive, ERα-negative breast cancers have also been shown to express AR." (PMID 22321971, 2012). "To date, neither ESR2 nor AR genes has been identified by breast cancer GWAS." (PMID 22792352, 2012). "The role of AR in breast cancer has not yet been fully elucidated, but it has been postulated that AR has an anti-proliferative and favourable prognostic effect in ER-positive breast cancer, whereas it has a growth-stimulating and unfavourable prognostic effect in ER-negative breast cancer." (PMID 22899999, 2012). "Therefore, a combination therapy strategy with AR and MEK inhibitors may provide an attractive therapeutic option for the ER-/AR+ subtype of breast cancer." (PMID 21457548, 2011). "Therefore, a combination therapy strategy with AR and MEK inhibitors may provide an attractive therapeutic option for molecular apocrine breast cancer." (PMID 21457548, 2011). "In addition, other studies have not found any significance of AR expression in predicting prognosis in breast cancer." (PMID 18507821, 2008). "Even so, in despite of assuming an association between AR expression and some MMPs/TIMPs production in the context of breast cancer, we could not determine any significant relationship between AR status and the occurrence of distant metastases." (PMID 18507821, 2008). "Three categories had median P values below 0.001 (FDR = ~0): breast cancer estrogen signaling; MSigDB's set of ER-upregulated genes identified by Frasor and coworkers; and drug resistance and metabolism, which contains ESR1, BCL2, AR and ER's co-regulator ERBB4." (PMID 17845722, 2007). "Furthermore, AR-targeted therapies may offer a novel treatment avenue for human breast cancer patients, especially for those with AR-positive, estrogen receptor-negative or triple-negative subtypes, which are often resistant to conventional treatments." (PMID 40286049, 2025). "Most breast cancers express AR, regardless of whether they express ER." (PMID 40023399, 2025). "However, the ability of AR to regulate C/EBPβ expression in breast cancer has not been studied." (PMID 40448099, 2025). "Patients with AR positive versus AR negative BrM had similar overall survival (12.5 vs. 7.9 months, p = 0.6), brain-specific progression-free survival (8.0 vs. 5.1 months, p = 0.95), and time from breast cancer diagnosis to BrM diagnosis (51 vs. 29 months, p = 0.16)." (PMID 37345085, 2023). "In particular, AR is emerging as a potential weapon for managing ER-positive and triple-negative breast cancer (TNBC), which prognosis is still considerably poorer compared to the other BC subtypes due to the shortage of therapeutic options." (PMID 37568977, 2023). "Interestingly, recent studies reported that AR is expressed in 70–90% of all breast cancers and 22–35% of TNBC, suggesting that AR could be a potential therapeutic target for treating breast cancer." (PMID 35960413, 2022). "Evidence suggests that the AR might be a tumor suppressor in estrogen receptor alpha-positive (ERα+ve) breast cancer but a tumor promoter in estrogen receptor alpha-negative (ERα-ve) breast cancer." (PMID 36499670, 2022). "Breast carcinoma with apocrine differentiation or apocrine carcinoma (APO) is a rare subtype of invasive breast cancer (~ 1%) that has a characteristic apocrine morphology along with the androgen receptor (AR) expression and the lack of estrogen receptor (ER) activity." (PMID 35355162, 2022). "Additionally, dual inhibition or degradation of AR and ER is not sufficient, in most models, to radiosensitise AR+/ER+ breast cancer cells in vitro suggesting that these receptors may not be compensating for each other when co-expressed." (PMID 35618789, 2022).
breast carcinoma (continued). "In addition, since rapid androgen actions have been reported in classical AR-lacking breast cancer models and membrane androgen binding sites have been observed in breast carcinoma cells, OXER1 has been recently proposed as a potential drug target in breast cancer." (PMID 34831222, 2021). "However, the therapeutic effect of AR/ER ratio on breast cancer has not been fully determined." (PMID 34886806, 2021). "AR is expressed in about 10–35% of triple negative breast cancer (TNBC), which does not express ER, PR and Her2/neu and tends to be more aggressive than other subtypes of BC." (PMID 33802610, 2021). "Finally, these findings are pertinent to the population of postmenopausal women with early stage ER+ breast cancer receiving letrozole and tamoxifen and may not necessarily reflect the influence of AR expression on the efficacy of other endocrine therapies." (PMID 30795773, 2019). "AR signalling influence on breast cancer depends on the contest of the different subtype of disease as indicated by a number of studies showing that the expression of AR is a favourable determinant of survival in estrogen receptor alpha (ERα)-positive, but not ERα-negative breast cancer patients." (PMID 31684907, 2019). "In conclusion, we demonstrated that the physical squelching of the AR/ER shared coactivator AIB1 may represent at least one of the several potential mechanisms through which AR can negatively modulate ERα-mediated signalling pathway and inhibit breast cancer cells proliferation." (PMID 31684907, 2019). "It should, however, be noted that splice variants of ESR1 in breast cancer differ importantly from splice variants of the AR, as ESR1 splice variants are also expressed in healthy breast tissue, and full‐length AR and splice variants are typically absent in CellSearch‐enriched fractions of HBDs." (PMID 29063679, 2018). "The prognostic discrepancy of AR in ERα-negative breast cancer may be also due to the differential molecular features of the ERα-negative tumors and the lower frequency of ERα-negative compared to ERα-positive breast cancers." (PMID 28474005, 2017). "Since it is not yet clear whether AR has a predominantly proliferative or anti-proliferative function, its biological role and significance as an independent predictor of clinical outcome in breast cancer remains controversial." (PMID 27548161, 2016). "Interestingly, a recent study indicated that in ERα-positive breast cancers treated with TAM the ratio of nuclear AR to ER (AR:ER) rather than the level of AR expression may play a role in disease progression and response to treatment." (PMID 27548161, 2016). "Importantly these findings open up the possibility of utilizing anti-androgens in the treatment of a specific subtype of breast cancer expressing high levels of AR and PSAP, which may not exhibit sustained response to endocrine therapy." (PMID 26341737, 2015). "Our results revealed that inhibiting CA1 expression could increase the expression of AR, suggesting that CA1 could regulate AR expression and might therefore influence the progression of microcalcification and other tumourigenic processes during breast cancer tumourigenesis." (PMID 26459317, 2015). "These discrepancies could be in part due to the lack of consistent application of the morphological criteria and the use of different methods and cut-offs values for positivity suggesting that hormonal status AR+/ER-/PR- may not be sufficient to discriminate IAC from other breast cancer subtypes." (PMID 25389781, 2014). "Thus, targeting AR may offer a potent form of hormone therapy for this group of patients, yet despite this, therapies targeting AR for breast cancer are currently not in widespread use." (PMID 22321971, 2012). "However, the status of AR by immunohistochemistry in other poorly differentiated carcinomas that may enter in the differential diagnosis for mammary carcinoma has not been evaluated previously." (PMID 17020615, 2006).
breast carcinoma (continued). "In this study, we found that owing to the lack of AR expression in AR-TNBC, C/EBPβ was upregulated and enhanced the aggressive characteristics of breast cancer cells." (PMID 40448099, 2025). "The lead compounds showed a dual mechanism of action by inhibiting S6 kinase and promoting Bcl-2 phosphorylation at 0.9 μM, without significantly affecting hormonal breast cancer targets such as ERα, GREB1, and AR." (PMID 41463068, 2025). "PLA-detected interactions between AR and GATA3 were also evident in clinical primary ER+ /AR + (n = 2 cases) and ER- /AR + (n = 2 cases) breast cancers as well as non-malignant breast tissues from reduction mammoplasties (n = 2 cases)." (PMID 38317241, 2024). "Triple-negative (negative for ER/PgR/HER2) breast cancer (TNBC) can be molecularly classified as basal-like, luminal-AR (androgen receptor), immune-activated, and claudin-low." (PMID 37934318, 2024). "Taken together, these results indicate that GATA3 facilitates but is not essential for AR chromatin binding and implicate GATA3 as an AR co-activator in breast cancer cells." (PMID 38317241, 2024). "Even though AR is expressed in over 70% of estrogen receptor (ER)-positive and in up to 45% of triple-negative breast cancer (TNBC), its role in breast cancer (BC) has not been completely elucidated." (PMID 37902839, 2024). "Our AR RIME data is consistent with these MDA-MB-453 studies but does not rule out an interaction between AR and FOXA1 in the other breast cancer models." (PMID 38317241, 2024). "Activated AR has been shown to cooperate with HDAC1, HDAC2, or HDAC3 to downregulate E-cadherin and promote the migration of non-metastatic breast cancer cells." (PMID 39000339, 2024). "Androgen receptor (AR) status subclassifies triple-negative breast cancer (TNBC) into AR-positive TNBC (AR+ TNBC) and AR-negative TNBC or quadruple-negative breast cancer (AR− or QNBC)." (PMID 39769441, 2024). "AR and GATA3 interact to transcriptionally regulate luminal epithelial cell differentiation in breast cancer regardless of ER status." (PMID 38317241, 2024). "COX multivariate regression analysis showed that AR was not a predictor of recurrence and metastasis of HR-/HER2 + breast cancer." (PMID 37099044, 2023). "As expected, ASR-600 failed to inhibit the growth of breast cancer cells, which supports the notion that ASR-600 specifically targets AR in CaP cells." (PMID 36937838, 2023). "What is the relationship between AR expression and immune infiltration in HER2+ nonmetastatic breast cancer?" (PMID 37085500, 2023). "While TNBC has been well characterized, recent studies have identified a highly aggressive androgen receptor (AR)-negative subtype of TNBC, quadruple-negative breast cancer (ER/PR-, HER2-wildtype, AR-; QNBC)." (PMID 36139643, 2022). "While seviteronel is both a CYP17 and AR inhibitor, CYP17 is not commonly expressed in breast cancer cell lines, and the culture media used has supplemented cholesterol and steroid hormones, thus preventing cells from relying on CYP17 for androgen production." (PMID 35618789, 2022). "While radiosensitising in AR + TNBC, AR inhibition does not modulate radiation sensitivity in AR+/ER+ breast cancer." (PMID 35618789, 2022). "Studies on the correlation between AR and prognosis and its function in luminal B (HER–2 negative) breast cancer were contradictory." (PMID 36556209, 2022). "Currently, no study has focused on the relationship between AR expression and the response to neoadjuvant therapy including HP in HER2-positive breast cancer patients." (PMID 35207749, 2022). "On the contrary, quadruple negative breast cancers (QNBCs), so those that lack in ER, PR, HER2, and AR expressions, are considered more aggressive with the worst prognosis." (PMID 36294994, 2022). "The relationship between AR expression and prognosis in luminal B HER–2 positive breast cancer is not clear, and the conclusions of different studies are inconsistent." (PMID 36556209, 2022).